RN7SL443P (RNA, 7SL, cytoplasmic 443, pseudogene)
Gene: Miscellaneous RNA gene on chromosome 20 (44,007,248 to 44,007,537, forward strand). Ensembl gene ENSG00000241229.
Homologues: Orthologues: chimpanzee Metazoa_SRP (98% identical), macaque Metazoa_SRP (91% identical). Paralogues in human: RN7SL2 (83% identical), RN7SL1 (82% identical), RN7SL3 (81% identical), RN7SL300P (81% identical), RN7SL769P (80% identical), RN7SL45P (80% identical), RN7SL186P (79% identical), RN7SL296P (79% identical), RN7SL386P (79% identical), RN7SL543P (79% identical), RN7SL615P (79% identical), RN7SL650P (79% identical), and 704 more.